MEOX2 (mesenchyme homeobox 2)
Diseases named in the same sentence as MEOX2 in open-access papers (continued):
Sharing a sentence is not in itself a finding about the gene and the disease.
lung carcinoma (14 papers, 2013 to 2025). "This supports previous research showing that lung cancer patients with lower MEOX2 expression and EGFR mutations had better overall survival with combined cisplatinum and TKI therapy." (PMID 39971779, 2025). "MEOX2, a homeobox gene, has been implicated in promoting angiogenesis and tumor progression in glioblastoma and lung cancer through the regulation of the cell cycle and vascular factors." (PMID 40567599, 2025). "In lung cancer, overexpression of MEOX2 has been associated with chemoresistance and prognosis, whereas patients with lower MEOX2 expression had shorter survival times in hepatocellular carcinoma and larynx carcinoma." (PMID 35436995, 2022). "Here, an epigenomic strategy was implemented to identify novel MEOX2 gene promoter transcription targets and propose a new molecular mechanism underlying lung cancer drug resistance and poor clinical prognosis." (PMID 28978016, 2017). "Recently, MEOX2 has been implicated in fetal lung development and histopathological lung cancer progression, and MEOX2 and TWIST1 were previously associated with chemoresistance and lung cancer prognosis." (PMID 28978016, 2017). "However, the mechanisms associated with HOX-related genes such as MEOX2 in the context of lung cancer drug resistance, overall survival, and clinical prognosis has yet to be fully elucidated." (PMID 28978016, 2017). "Lung cancer remains the leading cause of cancer-related mortality globally, with genes such as SMARCB1, MEOX2, and GLI-1 playing significant roles in its malignancy." (PMID 39971779, 2025). "Oncology research indicates how MEOX2 influences lung cancer pathogenesis, demonstrating its influence on key cancer hallmarks, including cellular proliferation, invasion, metastasis, angiogenesis, and drug resistance." (PMID 39971779, 2025). "In lung cancer, miR-301 has been reported to target MEOX2, while in breast cancer, it targets COL2A1, PTEN, BBC3, and FOXF2." (PMID 37509289, 2023). "Reduced MEOX2 expression has been shown to be significantly correlated with short OS in hepatocellular and larynx carcinoma, whereas in lung cancer, MEOX2 overexpression has been demonstrated to be correlated with chemoresistance." (PMID 38090653, 2022). "Among homeobox genes involved in cancer, MEOX2 has recently been described as a possible actor of carcinogenesis in Wilms tumor, lung cancer, and in laryngeal cancers." (PMID 34885053, 2021). "Previous studies showed that miR-301a activated ERK/CREB pathways by targeting MEOX2 in lung cancer cells." (PMID 31762806, 2019). "Here, we describe for the first time a MEOX2 gene promoter target profile in the context of transcriptionally active RNA Pol II enzyme in lung cancer." (PMID 28978016, 2017). "Through bioinformatics analysis, we observed the enriched MEOX2 occupation of gene promoter sequences (Log2 above 532 nm fluorescence) versus RNA Pol II occupation (Log2 below 635 nm fluorescence) in the lung cancer patients designated P-13, P-6 and P-3." (PMID 28978016, 2017). "The miR-301a-3p had been reported to target MEOX2 in lung cancer, FOXF3, BBC3, PTEN and COL2A1 in breast cancer and RUNX3 in gastric cancer." (PMID 26019136, 2015). "MEOX2 was uniformly higher methylated in all lung cancer samples, while the methylation of the other three genes was correlated with either the differentiation status of the tumor (MDK, LAPTM5) or with the tumor histopathological type (FGFR3)." (PMID 23086271, 2013). "Therefore, by use of shSMARCB1, we downregulated SMARCB1 genetic expression and protein levels, identifying a significant decrease in MEOX2 expression and protein levels in A549 lung cancer cells." (PMID 39971779, 2025). "Furthermore, this study suggests that epigenetic regulators, including the NuRD (MTA2) and ncBAF (BRD9) complexes, contribute to EGFR and GLI-1 expression and interact with MEOX2 in lung cancer cells." (PMID 39971779, 2025).
lung carcinoma (continued). "MEOX2 is known to modulate the ERK/MAPK pathway in the A549 cell line derived from lung carcinoma, which may suggest that MEOX2 affects cell viability may be driven by the ERK/MAPK pathway." (PMID 34885053, 2021). "Looking at the top SNP pairs, we observe the second highest SNP pair map to NXN and MEOX2 genes, suggesting their interaction might be key to understanding lung cancer." (PMID 32957998, 2020). "However, the identities of MEOX2 gene promoter targets, as well as related epigenetic profiles and molecular mechanisms involved in cancer drug resistance and clinical lung cancer prognosis, have remained unclear." (PMID 28978016, 2017). "Recent published reports suggest MEOX2 overexpression accompanied by epigenetic events constitutes a probable new cancer drug resistance mechanism that must be considered in the context of lung cancer clinical management." (PMID 28978016, 2017). "Furthermore, MEOX2 is also suggested to be affected in lung cancer." (PMID 32957998, 2020). "Similar effects were seen with siRNA-GLI1 or a mixture of siRNA-MEOX2 plus siRNA-GLI1, but no significant reduction in cellular viability occurred with either anti-MEOX2 or anti-GLI-1 siRNAs in an EGFR-mutated lung cancer cell line H1975 with non-detectable MEOX2 mRNA expression." (PMID 28978016, 2017). "Subsequently, this positive co-expression among both low and high protein expression lung cancer patient groups was quantitatively detected in the INCAN patient cohort by undertaking an Intensity Index analysis based on Algorithm Positive Pixel Bin Counts for MEOX2 and GLI-1." (PMID 28978016, 2017). "Overall, these results suggest that MEOX2 and GLI-1 play divergent roles in lung cancer progression, and response to EGFR-TKIs-based therapy, with both MEOX2/GLI-1 potentially influencing EGFR gene expression." (PMID 39971779, 2025). "To assess the clinical significance of MEOX2 and GLI-1 expression in lung cancer, we analyzed the TCGA Lung Cancer dataset, focusing on PFI curves in early-stage patients." (PMID 39971779, 2025). "Indicating how MEOX2 and GLI-1 regulate the abundance of oncogenic and epigenetic markers through lung cancer in vivo progression, suggesting their critical roles in the modulation of lung tumor biology." (PMID 39971779, 2025). "Based on this, we conducted Co-IP assays using A549 lung cancer cells, which revealed that SMARCB1 interacts with MEOX2, GLI-1, and BRD9, with a potential weak interaction with CBP and EZH2." (PMID 39971779, 2025). "In conclusion, this study reveals the critical roles of MEOX2, GLI-1, and SMARCB1 as tumor biomarkers in human lung cancer progression." (PMID 39971779, 2025). "Furthermore, survival curve analysis of all INCAN lung carcinoma patients with EGFR-non-mutated status identified a better overall survival index (statistically significant at p≤0.005) with lower MEOX2 and GLI-1 protein expression levels (p=0.122 and p=0.002, respectively)." (PMID 28978016, 2017). "Results showed a significant decrease in EGFR, CBP, and SMARCB1 at mRNA and protein levels, and a significant increase in mRNA of EZH2, but no significant change in protein levels for EZH2, suggesting that both MEOX2/GLI-1 modulate these tumor and epigenetic markers in lung cancer A549 cells." (PMID 39971779, 2025). "Our study reveals how MEOX2 and GLI-1 are key molecular modulators of the GLI-1 and EGFR-epigenetic patterns, which in turn transcriptionally and epigenetically affect EGFR gene expression in lung cancer." (PMID 39971779, 2025). "In conclusion, our results suggest novel molecular mechanisms whereby MEOX2 and GLI-1 may modulate functional dynamics between cBAF (SMARCB1) and ncBAF (BRD9) complexes, contributing to lung cancer progression." (PMID 39971779, 2025). "Our results suggest that MEOX2, HDAC9, TWIST1, AhR and EVX1 overexpression from the 7p21 locus may be novel lung cancer or NSCLC tumor markers." (PMID 25460568, 2014).
lung carcinoma (continued). "We also validated the role of the MEOX2-GLI1 axis by performing transwell-migration vertical assays with both the A549 and NH2347 lung adenocarcinoma cell lines and observed significant differences (p≤0.001) compared with H1975 lung cancer cells, which express non-detectable MEOX2 levels." (PMID 28978016, 2017).
glioblastoma (8 papers, 2020 to 2025). The most malignant astrocytic tumor (WHO grade IV). "MEOX2 expression was described as part of the molecular signature of the CL subtype and was included in a 17-gene high-risk signature correlating with overall survival in mesenchymal glioblastomas." (PMID 35565433, 2022). "EGFR and MEOX2 overexpression have been implicated before as drivers of glioblastoma growth." (PMID 34584066, 2021). "Even more recently, a paper described the nuclear localization of MEOX2 in both GSCs and in glioblastoma tissues, suggesting its potential involvement in GSC phenotype and adhesion properties." (PMID 35565433, 2022). "In the context of the well-known heterogeneity of glioblastoma and of its initiating cells, this points to the significance of MEOX2 enrichment in GSCs." (PMID 35565433, 2022). "Herein, we show that MEOX2 is strongly overexpressed in GSCs compared to stable cell lines, and we demonstrate that MEOX2 function is important for specific features of glioblastoma stem cells, in particular their survival and their ability to form spheres." (PMID 35565433, 2022). "An in silico study of the regulatory regions of genes differentially expressed by MEOX2 knock-down revealed that they mainly consisted of GC-rich regions enriched for Sp1 and Klf4 binding motifs, two main regulators of metabolism in glioblastoma." (PMID 35565433, 2022). "Mesenchyme homeobox 2 (MEOX2) is a transcription factor overexpressed in glioblastoma, whose expression is negatively correlated with patient survival." (PMID 35565433, 2022). "We unraveled the MEOX2 contribution to cell viability and growth and its potential involvement in phenotype and adhesion properties of glioblastoma cells." (PMID 34885053, 2021). "As a whole, this set of genes modulated in response to MEOX2 knock-down may represent a core collection of MEOX2 regulated genes in glioblastoma stem cells." (PMID 35565433, 2022). "However, the investigation of the role of MEOX2 in glioblastoma stem cells is in its infancy, and we still need to understand the molecular mechanisms linking MEOX2 with the onset and aggressiveness of glioblastoma." (PMID 35565433, 2022). "Conversely, MEOX2 has been reported to downregulate in glioblastoma cell lines compared to normal astrocytes; thus, it could be an antioncogene." (PMID 35646656, 2022). "This favors a stem-specific expression/role of MEOX2, at least in the context of glioblastoma." (PMID 35565433, 2022). "Indeed, in the original subtyping classification of glioblastomas, MEOX2 was initially reported as a marker of the CL subtype, and more recently, MEOX2 was shown to be aberrantly activated and one of the master transcription factors in Group 1 GSCs." (PMID 35565433, 2022). "We searched the transcriptome of the MEOX2 depleted cells to investigate the basis of the observed phenotypes, and, in line with the known great variability of glioblastoma stem cells, we found a large number of genes modulated by MEOX2 knock-down that were different in the two GSC lines we assayed." (PMID 35565433, 2022). "Our results reveal a novel function for MEOX2 in glioblastoma and suggest a mechanism through which GSCs may survive even in unfavorable conditions." (PMID 35565433, 2022). "We analyzed the MEOX2 expression in six patient-derived GSCs populations and found that it was strongly expressed in all cell lines, whereas it was absent or barely expressed in all other non-stem samples used as controls, either healthy brain tissue and astrocytes or stable glioblastoma cell lines." (PMID 35565433, 2022). "The four metabolic genes whose repression is shared in both the BT273 and BT379 cell lines when MEOX2 is knocked down are all known to be induced by hypoxia and play a key role in the glycolytic pathway and have all been proposed as possible therapeutic targets for glioblastoma." (PMID 35565433, 2022).
glioblastoma (continued). "Our results indicate that immunohistochemical detection of EGFR, MEOX2, SOX11, and INSM1 can be useful for detection of glioblastoma cells in limited histological samples, especially when used in combination." (PMID 37568909, 2023). "Compared to IDH1-mutant tumours, glioblastomas showed significantly higher expression of EGFR, MEOX2, and CD34 and significantly lower positivity for SOX11." (PMID 37568909, 2023). "We were intrigued by the extreme overexpression of MEOX2 in all six GSC samples we analyzed, possibly indicating a role for this factor in glioblastoma initiating cells." (PMID 35565433, 2022). "Several reports have suggested that high expression of homeotic genes, including HOXA9, HOXA13, mesenchyme HOX2 (MEOX2), and HOXD4 is an indicator of poor prognosis in glioblastoma (GBM) patients." (PMID 34458259, 2021). "Another protein, mesenchyme homeobox 2 (MEOX2), is often overexpressed in glioblastomas." (PMID 37568909, 2023). "As previously shown by us and others, MEOX2 is known to be overexpressed in glioblastomas compared to healthy brain cells, and our present data further highlighted that GSC lines express MEOX2 while established non-stem glioblastoma cell lines essentially lack its expression." (PMID 35565433, 2022).
laryngeal carcinoma (7 papers, 2021 to 2025). Carcinoma that arises from the laryngeal epithelium. "The genes are associated with laryngeal cancer (MEOX2), cervical cancer (FGF7), oral cancer (DPT), breast cancer (CILP) or ovarian cancer (TMEM119) and LAMP3-positive dendritic cells are generally associated with cancer." (PMID 38671536, 2024). "Reduced expression of MEOX2 is associated with poor prognosis in hepatocellular carcinoma and laryngeal cancer, but there are few reported studies on breast cancer." (PMID 35615155, 2022). "Studies have discovered that over-expression of MEOX2 promoted apoptosis through inhibiting the PI3K/Akt pathway in laryngeal cancer cells." (PMID 37178414, 2023).
breast carcinoma (6 papers, 2015 to 2024). "Our study revealed that the angiogenesis-associated gene MEOX2 can be used as a novel biomarker for breast cancer diagnosis and clinical therapy." (PMID 35615155, 2022). "Thus, we confirmed that MEOX2 expression was low in breast cancer tissues and was associated with angiogenesis." (PMID 35615155, 2022). "Thus, we identified a crucial angiogenesis-associated gene MEOX2 in breast cancer." (PMID 35615155, 2022). "The prognostic value of the MEOX2 gene in breast cancer tissue was evaluated with the Kaplan-Meier plotter." (PMID 35615155, 2022). "Further analysis of the DEGs with GEPIA and UALCAN revealed that MEOX2 was significantly down-regulated and had different expression levels in different breast cancer subtypes." (PMID 35615155, 2022). "Surprisingly, when breast cancer patients were treated with the anti-tumor drug everolimus, the expression of MEOX2 was significantly up-regulated." (PMID 35615155, 2022). "Next, the expression level of MEOX2 was assessed in breast carcinoma cell lines (MCF-7 and SUM159PT) and the normal human mammary epithelial cell line, MCF-10A." (PMID 35615155, 2022). "The prognostic value of the MEOX2 gene was assessed in the Kaplan-Meier plotter online database by analyzing the overall data for breast cancer patients." (PMID 35615155, 2022). "To summarize, we conducted bioinformatics analyses of the angiogenesis-related DEGs in breast cancer and identified the significantly down-regulated gene MEOX2 based on the TCGA and GEO databases." (PMID 35615155, 2022). "The expression of MEOX2 in breast cancer samples was also significantly lower than that in normal control samples." (PMID 35615155, 2022). "Our experiments showed that MEOX2 expression in breast cancer tissues was significantly lower than that in adjacent normal tissues." (PMID 35615155, 2022). "Our research indicates that MEOX2 can be used as a novel biomarker for breast cancer diagnosis and clinical therapy." (PMID 35615155, 2022). "The results showed that MEOX2 expression in breast cancer tissues was significantly lower than that in adjacent normal tissues (p < 0.001)." (PMID 35615155, 2022). "The IHC results confirmed that MEOX2 expression was repressed in breast cancer tissues and the relatively low level indicated the tissue was densely vascularized." (PMID 35615155, 2022). "The Kaplan–Meier plotter online database showed that high expression of MEOX2 was significantly correlated with better survival in breast cancer patients, and the same conclusion was obtained in ER-positive and HER2-negative subgroups." (PMID 35615155, 2022). "The hazard ratios (HRs) and p values (log-rank test) showed that high expression of MEOX2 was significantly correlated with better survival in breast cancer patients." (PMID 35615155, 2022). "Using the GEO dataset, we found that the expression of MEOX2 presented an increasing trend both when breast cancer patients were treated with anti-tumor drugs and when breast cancer cells were treated with anti-carcinogenic compounds." (PMID 35615155, 2022). "The expression of the mesenchyme homeobox 2 (MEOX2) in breast cancer cells and tissues was assessed by quantification real-time polymerase chain reaction (qRT-PCR) and immunohistochemistry (IHC), respectively." (PMID 35615155, 2022). "The results showed that the expression of MEOX2 was lower in breast cancer tissues with different molecular subtype compared to normal tissues." (PMID 35615155, 2022). "Moreover, we found that the expression of MEOX2 in breast cancer cells after I3C treatment was significantly higher than that in the dimethyl sulfoxide (DMSO) vehicle group included in the GEO dataset." (PMID 35615155, 2022). "We found that MEOX2 expression was low in breast cancer and our findings suggested that MEOX2 may repress the occurrence of tumors by inhibiting angiogenesis." (PMID 35615155, 2022).
breast carcinoma (continued). "Further analysis and experiments revealed that MEOX2 may be related to the prognosis and treatment of breast cancer." (PMID 35615155, 2022). "Moreover, MEOX2 expression was significantly elevated in breast cancer cells after treatment with cisplatin (DDP) and epirubicin (EPI)." (PMID 35615155, 2022). "The high expression level of MEOX2 can enhance the growth of breast cancer." (PMID 31874629, 2019).
Alzheimer disease (4 papers, 2021 to 2025). A progressive, neurodegenerative disease characterized by loss of function and death of nerve cells in several areas of the brain leading to loss of cognitive function such as memory and language. "GWAS identified rare copy number variants in the MEOX2 gene that are associated with early and severe phenotypes of Alzheimer’s disease." (PMID 40870024, 2025). "MEOX2 expression is significantly low in Alzheimer’s disease neuro vasculature, causing vessel malformation and regression leading to reduced capillary density and CBF." (PMID 37511274, 2023). "Reduction of MEOX2 expression has been shown in brains of Alzheimer’s disease patients, and its haploinsufficiency was reported to lead to neurovascular dysfunction and susceptibility to Amyloid‐β toxicity in Meox2+/− mice." (PMID 35029322, 2022). "The top upstream regulator of blood nPM-DEGs was mesenchyme homeobox 2 (MEOX2), which regulates vertebrate limb myogenesis, and is also involved in neurovascular dysfunction in Alzheimer's disease." (PMID 34429070, 2021).